PBXIP1 (PBX homeobox interacting protein 1)
Description:
Regulator of pre-B-cell leukemia transcription factors (BPXs) function. Inhibits the binding of PBX1-HOX complex to DNA and blocks the transcriptional activity of E2A-PBX1. Tethers estrogen receptor-alpha (ESR1) to microtubules and allows them to influence estrogen receptors-alpha signaling.
Synonyms: HPIP
Tractability: PROTAC: ubiquitination databases record sites on it; its protein half-life has been measured.
Gene: Protein-coding gene on chromosome 1 (154,944,059 to 154,956,451, reverse strand). Ensembl gene ENSG00000163346.
Subcellular location: Cytoplasm, cytoskeleton; Nucleus
Subcellular location (Human Protein Atlas): Nucleoplasm; Cytosol
Gene Ontology:
Molecular function: DNA-binding transcription factor binding; protein binding; transcription corepressor activity; transcription coregulator activity; transcription coactivator activity
Biological process: hemopoiesis; negative regulation of DNA-templated transcription; regulation of DNA-templated transcription; positive regulation of DNA-templated transcription
Cellular component: cytosol; nucleoplasm; nucleus; chromatin; cytoplasm; cytoskeleton; transcription regulator complex
Genetic constraint (gnomAD): Loss-of-function variants: 72 observed, 74.01 expected, observed/expected ratio (o/e) 0.97, 90% interval 0.8 to 1.18. The upper end of that interval is the gene's LOEUF score, 1.18, which puts it in group 5 of 6, group 1 being the genes least tolerant of losing a copy. Missense variants: 818 observed, 941.06 expected, observed/expected ratio (o/e) 0.87, 90% interval 0.82 to 0.92. Synonymous variants: 330 observed, 380.22 expected, observed/expected ratio (o/e) 0.87, 90% interval 0.79 to 0.95.
Homologues: Orthologues: chimpanzee PBXIP1 (98% identical), macaque PBXIP1 (95% identical), pig PBXIP1 (77% identical), guinea pig PBXIP1 (74% identical), mouse Pbxip1 (71% identical), dog PBXIP1 (71% identical), rat Pbxip1 (70% identical).
Diseases named in the same sentence as PBXIP1 in open-access papers:
PBXIP1 is named in the same sentence as 27 diseases in open-access papers, as found by Europe PMC text mining. Sharing a sentence is not in itself a finding about the gene and the disease. The quoted sentences say what the papers report.
deafness (2 papers, 2024 to 2025). An inherited or acquired condition characterized by the complete loss of the ability to hear from one or both ears. "We detected FGF3 (p.Arg165Gly) and GREB1L (p.Cys186Arg), variants of uncertain significance in two recognized genes for deafness, and PBXIP1(p.Trp574*) in a candidate gene." (PMID 38947059, 2024).
ependymoma (2 papers, 2015 to 2022). A WHO grade II, slow growing tumor of children and young adults, usually located intraventricularly. "A recent study revealed that PBXIP1 is a novel protein overexpressed in astrocytoma and ependymoma that is involved in tumour cell proliferation and migration and warrants further exploration as a novel therapeutic target in these tumours." (PMID 36117173, 2022). "Similar overexpression of PBXIP1 was also found in high-grade glioma and ependymoma, oral squamous cell carcinoma and liver cancer." (PMID 26497366, 2015).
leukemia (2 papers, 2023 to 2026). A malignant (clonal) hematologic disorder, involving hematopoietic stem cells and characterized by the presence of primitive or atypical myeloid or lymphoid cells in the bone marrow and the blood. "While PBX1 has been extensively studied in leukemia, little is known about the contributions of PBXIP1 and PBX4 in this context." (PMID 41554854, 2026). "PBXIP1 protein is a suppressive regulator of pre-B-cell leukemia transcription factors, and it also interacts with estrogen receptor α and β (ERα, ERβ)." (PMID 37143779, 2023). "This warrants further investigation into the specific contributions of PBXIP1 and PBX4 to MNX1-driven leukemia and their potential as therapeutic targets." (PMID 41554854, 2026). "Together, these results suggest that while Pbx1 functions as an early target of MNX1 in preleukemic cells, Pbxip1 and Pbx4 act as secondary (indirect) targets whose altered expression arises with MNX1 leukemia progression." (PMID 41554854, 2026). "However, PBXIP1 and PBX4 are less extensively studied in the context of leukemia." (PMID 41554854, 2026). "However, the expression of Pbx4 and Pbxip1 was not significantly affected by Sinefungin treatment, possibly due to their later induction during leukemia development." (PMID 41554854, 2026).
chronic kidney disease (1 paper, 2024). Impairment of the renal function secondary to chronic kidney damage persisting for three or more months. "Similarly, PBXIP1 is associated with renal fibrosis and chronic kidney disease, while SPP1 is related to damage in renal tubules." (PMID 39086896, 2024).
leiomyosarcoma (1 paper, 2015). An uncommon, aggressive malignant smooth muscle neoplasm, usually occurring in post-menopausal women. "Moreover, an amplified copy number of PBXIP1 was found to be predictive of poor outcomes in undifferentiated pleomorphic sarcomas and leiomyosarcomas." (PMID 26497366, 2015).
lung adenocarcinoma (1 paper, 2015). A carcinoma that arises from the lung and is characterized by the presence of malignant glandular epithelial cells. "Little direct evidence has been published for the carcinogenic role of PBXIP1 in lung adenocarcinoma." (PMID 26497366, 2015). "Furthermore, a prognostic significance for the CNVs of TERT and PBXIP1 in lung adenocarcinoma was found, which may lead to translation into the clinic and improve outcomes for patients with this fatal disease." (PMID 26497366, 2015). "Also, the CNVs of PBXIP1 and TERT presented significant upregulation of corresponding gene expressions and were found to be independently predictive of lung adenocarcinoma patient survival." (PMID 26497366, 2015). "In addition, the combined effect of the CNVs of PBXIP1 and TERT on lung adenocarcinoma prognosis was assessed." (PMID 26497366, 2015).
schizophrenia (1 paper, 2023). A major psychotic disorder characterized by abnormalities in the perception or expression of reality. "TNC gene PBXIP1 protein were both decreased in schizophrenia in this analysis, and it might be possible that both were decreased in association with reduced hippocampal function and neurogenesis." (PMID 37143779, 2023).
cancer (3 papers, 2019 to 2024). A tumor composed of atypical neoplastic, often pleomorphic cells that invade other tissues. "Although PBXIP1 has been reported to be related to diverse biological processes such as hematopoiesis, estrogen signaling‐related cellular function, reproduction biology, and cancers since its discovery in 2000, the role of PBXIP1 on AD is rarely studied." (PMID 37984333, 2024). "For unreported model genes (MPZ, SCARA3, MPP2 and PBXIP1), recent studies have demonstrated that those genes are involved in the development of cancers." (PMID 36117173, 2022). "Previously, we and others have shown that hematopoietic pre-B cell leukemia transcription factor-interacting (PBX-interacting) protein (HPIP/PBXIP1) mainly functions as a modulator of cancer carcinogenesis and progression." (PMID 30659184, 2019).
tumor (3 papers, 2005 to 2024). "IHC analysis of xenografted tumour tissues revealed that MPZ, SCARA3, MPP2 and PBXIP1 expression levels were low in the SW620/sh-MPZ, SW620/sh-SCARA3, SW620/sh-MPP2 and SW620/sh-PBXIP1 groups." (PMID 36117173, 2022). "At variance with the previously quoted tumor-inducing role in this type of cancer, other authors reported overexpression of the PBX1 inhibitor PBXIP1 in gastric cancer patients, leading to repressed PBX1 transcriptional activity and promotion of cell proliferation, migration, and invasion." (PMID 38404687, 2024).
infection (1 paper, 2025). The state of being infected such as from the introduction of a foreign agent such as serum, vaccine, antigenic substance or organism. "Upon infection, PbXIP1 is strongly upregulated and secreted into the apoplast, where it significantly inhibits CfXyn11A activity and enhances pear disease resistance." (PMID 40619424, 2025).
PBXIP1 also shares sentences with these, for which no sentence is quoted: abortion (1 paper); Alzheimer disease (1); astrocytoma (1); brain tumors (1); cardiac hypertrophy (1); cardiomyopathy (1); colorectal tumour (1); dementia (1); gastric carcinoma (1); glioma (1); heart disease (1); hepatocellular carcinoma (1); liver cancer (1); Obesity (1); oral squamous cell carcinoma (1); renal fibrosis (1); sarcoma (1).